FGFR3 (fibroblast growth factor receptor 3)
Diseases named in the same sentence as FGFR3 in open-access papers (continued):
Sharing a sentence is not in itself a finding about the gene and the disease.
bladder cancer (continued). "As discussed by Serizawa, results also showed that FGFR3 mutation in bladder cancer when combined with methylation markers (APC, RASSF1A and SFRP2) provided a sensitivity of 90% to identify bladder tumors." (PMID 22530128, 2012). "Several urine-based genetic assays have been developed to detect FGFR3 mutations in patients with bladder cancer with sensitivity ranging from 58–92%." (PMID 22873290, 2012). "The most well-known association with FGFR mutations is the FGFR3 mutation observed in bladder cancer, in which somatic mutations in coding regions are observed in about 50% of all specimens." (PMID 22240789, 2012). "Eight common FGFR3 mutations in 3 exons (exons 7, 10, and 15) are associated with >90% of all known mutant FGFR3 positive bladder cancers." (PMID 22873290, 2012). "Replacement of a hydrophobic residue with a glutamic acid in FGFR3 (A391E) has been identified both in the germline of patients with Crouzon syndrome and as a somatic mutation in bladder cancer." (PMID 22383975, 2012). "Analysis of mutations in the FGFR3 gene, using the urine based CertNDxTM Bladder Cancer Assay, detected cancer indicating that the tumor was malignant; which was subsequently confirmed by pathology." (PMID 22873290, 2012). "Translocations involving FGFR3, as well as activating somatic mutations in FGFR3 have been identified in multiple myeloma and bladder cancer." (PMID 21666749, 2011). "FGFR3 mutations were mutually exclusive with RAS mutations in accordance with their signaling through the same pathway in bladder cancer." (PMID 21072204, 2010). "We have recently shown that with FGFR3 mutation analysis on urine samples from bladder cancer patients it was possible to detect recurrent tumors." (PMID 21072204, 2010). "We have previously shown that FGFR3 mutation analysis on urine samples from bladder cancer patients was able to detect recurrent tumors." (PMID 21072204, 2010). "The role of FGFR3 mutations in bladder cancer has been intensively studied in the last decade and it has been shown that activating mutations of FGFR3 is related to tumors of low grade and with good prognosis." (PMID 18237400, 2008). "FGF pathway genes, including FGF3, FGF4 and FGF8, are common targets of MMTV integration and FGFR3 mutations have been reported in 41% of bladder cancers." (PMID 18840272, 2008). "In bladder cancer, FGFR3 mutations have been associated with a prolonged survival and tumors carrying these mutations constitute a favorable disease category." (PMID 17311103, 2007). "Very frequent in bladder carcinoma, particularly in non invasive papillary tumours (pTa tumors) (70% of cases harbor mutations), FGFR3 mutations are more rare in multiple myeloma and cervical carcinomas." (PMID 15869706, 2005). "In bladder neoplasias, FGFR3 mutation characterizes low-grade low-stage pTa bladder tumors and is rarely found in advanced stage bladder carcinoma." (PMID 15869706, 2005). "In contrast, FGFR3 mutations are present in 17–20% of bladder cancers." (PMID 41514604, 2025). "To identify genes whose absence increases the sensitivity of bladder cells to erdafitinib, we performed genome‐wide CRISPR/Cas9 knockout library screen on MGH‐U3 (Y373C mutation) and SW780 (FGFR3‐BAIAP2L1 fusion) bladder cancer cell lines, both known to be FGFR3‐dependent." (PMID 40112217, 2025). "FGFR3 mutations play important oncogenic roles in bladder cancer." (PMID 41514604, 2025). "NUCB1, GSTM4, and FGFR3 had associations with bladder cancer risk." (PMID 38684708, 2024). "For example, higher FGFR3 was associated with an increased risk of bladder cancer." (PMID 38684708, 2024). "In addition to activating point mutations and fusions, wild type FGFR3 can contribute to tumorigenesis in bladder cancer." (PMID 39031286, 2024).
bladder cancer (continued). "In bladder cancer, about 20% of cases have FGFR3 mutations and fusions." (PMID 39796710, 2024). "Higher FGFR3 was associated with an increased risk of bladder cancer." (PMID 38684708, 2024). "Previous studies have indicated that somatic mutations in FGFR3 in bladder cancer patients could serve as potential predictive biomarkers for neoadjuvant chemotherapy response." (PMID 38911380, 2024). "Additionally, the occurrence of FGFR3 S249C mutation was less frequent in upper tract urothelial carcinoma patients compared to bladder cancer patients (37.5% vs. 59.3%)." (PMID 38831455, 2024). "31.7% of patients with bladder cancer had a somatic variant in FGFR3 gene." (PMID 39277826, 2024). "Alterations in FGFR3 also constitute critical mutations in bladder cancer, displaying strong associations with disease stage and grade; approximately 78.1% of patients with non-invasive bladder cancer showed FGFR3 expression, whereas the expression rate dropped to 18.2% in muscle-invasive cases." (PMID 39295845, 2024). "In addition, bladder cancers present mutations of FGFR3, which make them susceptible to treatment with FGFR inhibitors." (PMID 36902501, 2023). "Bladder cancer is typically associated with FGFR3 gene rearrangements." (PMID 37559152, 2023). "According to research, 50% of bladder cancers have somatic mutations of the FGFR3 gene." (PMID 37559152, 2023). "Hence, immunotherapy targeting the FGFR3 Y373C mutation would be one of the potential approaches for a subset of bladder cancer patients." (PMID 36831375, 2023). "FGFR3 expression is associated with an epithelial phenotype in bladder cancer cell lines." (PMID 36385700, 2023). "Studies have suggested that FGFR3 is associated with bladder cancer and multiple myeloma." (PMID 39380959, 2023). "The activating mutations of FGFR3 have been shown to promote a positive feedback in FGFR3 expression through the stabilisation of Myc (Myc proto-oncogene protein), resulting in the upregulation of FGFR3 in bladder cancers." (PMID 37997980, 2023). "FGFR3 expression was negatively associated with PD-L1 expression levels in bladder cancer tissues." (PMID 37215134, 2023). "Moreover, a phase II study (NCT04917809) recruits patients with recurrent non-invasive bladder cancer exhibiting FGFR3 mutations to evaluate erdafitinib." (PMID 37681152, 2023). "Therefore, NEDD4 targets PD-L1 for ubiquitination and destruction in FGFR3-overexpressing bladder cancer, indicating that NEDD4 is associated with immune surveillance via regulation of PD-L1 in bladder cancer." (PMID 37215134, 2023). "Accumulating evidence indicates that gain-of-function mutations in the FGFR3 gene may give rise to constitutive receptor activation and have been identified in bladder cancer and UTUC." (PMID 36675289, 2023). "Finally, the activity of CPL304110 in the second tumor model was also tested using a mutation in the FGFR3 gene—bladder cancer xenografts UM-UC-14." (PMID 38282676, 2023). "FGFR3 rearrangements and missense mutations were reported in bladder cancer." (PMID 37215134, 2023). "Finally, fibroblast growth factor receptor 3 (FGFR3) was the main differentially mutated gene in bladder carcinoma that we discovered after conducting a cross-study on DEGs and DMGs." (PMID 35991125, 2022). "The study also showed that FGFR3 was more prone to mutations in the low stromal group, and these mutations may generate tumor-specific neoantigens in bladder cancer." (PMID 35991125, 2022). "In our study, FGFR3 SVs in bladder cancer were significantly associated with a lower TMB." (PMID 36462464, 2022). "It is known that FGFR3 mutations are common in bladder cancer." (PMID 35384983, 2022). "FGFR3 aberrations are predominantly implicated in bladder cancer." (PMID 35494629, 2022).
bladder cancer (continued). "Fibroblast Growth Factor Receptor 3 (FGFR3) is an attractive therapeutic target in bladder cancer given the 10–30% prevalence of FGFR3 aberrations (activating mutations or aberrant gene fusions) in these tumours, and their preclinical sensitivity to FGFR-targeted therapy." (PMID 35501832, 2022). "Furthermore, R3mab was able to bind not only wtFGFR3 but also the most common FGFR3 mutants and inhibited proliferation as well as FGFR3 signaling in bladder cancer cells, exhibiting wild type and mutated variants of FGFR3." (PMID 34123841, 2021). "FGFR3 mutations, which are more frequently found in noninvasive bladder cancer than in muscle-invasive cancer, are associated with favorable features and prognosis compared with bladder cancers, showing FGFR3 overexpression only." (PMID 34768978, 2021). "Advanced bladder cancer with mutations in FGFR3 are associated with a lower inflammation signature." (PMID 34638374, 2021). "A large number of studies have confirmed that FGFR3 mutation is a common genetic activity in bladder cancer and has become a promising molecular target for recurrence, prognosis, and treatment targets in bladder cancer." (PMID 34496843, 2021). "To answer the question whether FGFR3 somatic mutations can modulate DNA methylation in urothelial carcinomas, we thus decided to analyze the DNA methylation landscape of 20 bladder cancer cell lines." (PMID 33397444, 2021). "For example, in our study, FGFR3 mutations could be predicted with an AUROC of 0.78 in bladder cancer." (PMID 35251119, 2021). "Interestingly, the missense mutations of FGFR3 are associated with higher FGFR3 mRNA and also protein expression in bladder cancer, but the mechanism behind this upregulation is unclear." (PMID 34638374, 2021). "High grade primary luminal bladder cancer was associated with low FGFR3 expression, and vice versa." (PMID 33238591, 2020). "However, FGFR3 activating mutations play a key role in the pathogenesis of bladder cancer and have been found in benign conditions such as seborrheic keratosis and epidermal nevi." (PMID 33317587, 2020). "Notably, higher rates of FGFR3 mutation occurred in bladder cancer tissues with low risk score compared with tumors with high risk score." (PMID 33408272, 2020). "The FGFR3 S249C mutation is relatively frequent in bladder cancer (66.6%)." (PMID 32962091, 2020). "Interestingly, FGFR3 mutations have been predominantly found in genetically stable bladder cancers with favorable prognoses." (PMID 33243261, 2020). "The role of FGFR3 gene in oncogenesis may even be at the pre-translational level: Has_circ_0068871, a circRNA product of FGFR3 gene transcription, is overexpressed in bladder cancer, and is associated with cancer cell proliferation and migration." (PMID 33224141, 2020). "Urothelial hyperplasia and early stage, noninvasive bladder cancer frequently exhibit mutations in the gene encoding fibroblast growth factor receptor 3 (FGFR3) as well as components of the phosphoinositide 2-kinase/AKT/mammalian target of rapamycin (PI3K/AKT/mTOR) pathway." (PMID 30670749, 2019). "In addition, some FGFR3 mutations have been associated with an improved prognosis and decreased risk of metastasis in epithelial tumors, including bladder carcinomas." (PMID 31619201, 2019). "The S249C and R248C variants of FGFR3 are often found in bladder cancers." (PMID 30577533, 2018). "Certain FGFR3 mutations are actionable in bladder cancer (OncoKB level 3)." (PMID 30442178, 2018). "However, FGFR3 is a growth factor receptor and is frequently subjected to activating mutations in low-grade bladder cancers." (PMID 29515890, 2018). "Furthermore, tumor-specific mutations and upregulation of FGFR3 mRNA were found in multiple myeloma, bladder carcinoma, cervical cancer, and colon carcinoma." (PMID 29850625, 2018).
bladder cancer (continued). "Interestingly, in patients with non-invasive bladder cancer after resection, the presence of an FGFR3 mutation in cells obtained from urinalysis at routine follow-up was predictive of disease recurrence." (PMID 28030802, 2017). "Furthermore, activating mutations and overexpression of FGFR3 have been reported in bladder cancers and multiple myeloma." (PMID 27154171, 2016). "We investigated the squamous differentiated bladder cancers for activating FGFR3 point mutations." (PMID 27669755, 2016). "More commonly, however, mutations in FGFR3 characterize bladder carcinoma." (PMID 26224133, 2015). "Catto was the first to associate miR-100 loss and upregulation of FGFR3 in low-grade bladder cancer, proposing that miR-100 loss could precede the FGFR3 mutation." (PMID 25493074, 2014). "A decreased rate of cell proliferation might indeed explain the less aggressive phenotypes frequently observed in FGFR3-mutated bladder carcinomas, in comparison with EGFR over-expression cases." (PMID 24250280, 2013). "In addition, activating mutant forms of FGFR3 attributed to point mutations are frequently detected in bladder cancer." (PMID 23900974, 2013). "Our model thus predicts that the strength/rapidity of PI3K activation versus SPRY-mediated ERK negative feedback could underly the less aggressive phenotypes observed in FGFR3-mutated bladder carcinomas." (PMID 24250280, 2013). "Deregulated genes during bladder cancer pathogenesis in the FGFR3-mutated tumor pathway." (PMID 22724020, 2012). "These mutations in the FGFR3 gene are largely bladder cancer specific, and it is suggested that the FGFR family may play an important role in bladder carcinogenesis." (PMID 17088904, 2006). "Notably, we observed similar findings in bladder carcinoma cell lines, suggesting that FGFR3 alterations (i.e., fusions, mutations) might alter the methylome via direct or indirect mechanisms." (PMID 33397444, 2021). "Similarly, grade of bladder cancer is inversely related to the frequency of driver FGFR3 mutations." (PMID 32066498, 2020). "Notably, in bladder cancer the frequency of FGFR3 overexpression is much higher than the frequency of FGFR3 mutations, indicating that in HPV+ HNSCC more tumors may be affected than can be found in a mutational analysis." (PMID 28525363, 2017). "In particular, activating FGFR3 mutations have been associated with growth arrest in chondrocytes, whereas they enhance proliferation and/or transformation in several cancer types and skin disorders (e.g. bladder cancer, multiple myeloma, seborrheic keratosis, etc.)." (PMID 24250280, 2013). "Finally, we are currently assessing a potential proliferative role of p38 in FGFR3-mutated bladder carcinomas (unpublished preliminary data), which might lead to further model refinement." (PMID 24250280, 2013). "Studies reporting the prevalence of FGFR3 alterations and/or nectin-4 expression in bladder cancer were included." (PMID 42278538, 2026).
bladder cancer (continued). "Genomic alterations in FGFR3 are well-established oncogenic drivers in bladder cancer and represent predictive biomarkers of response to FGFR-targeted therapies." (PMID 41681916, 2026). "LZU‐WZLYCS01 is a novel FGFR3‐targeting ADC for bladder cancer with 7‐ethyl‐9‐fluorocamptothecin (A2) as its cytotoxic payload." (PMID 41168906, 2026). "Collectively, these findings highlight the central role of FGFR3 splicing dysregulation in driving tumorigenesis and therapeutic vulnerability across colorectal, prostate, and bladder cancers." (PMID 41584352, 2026). "Clinically, therapeutic agents such as the selective FGFR inhibitor derazantinib and pan-FGFR inhibitor have shown promising efficacy in bladder cancers harboring FGFR3 alterations." (PMID 41584352, 2026). "AssureMDx analyzes DNA from exfoliated urothelial cells in urine to identify mutations (FGFR3, TERT, HRAS) and methylation changes (OTX1, ONECUT2, TWIST1), allowing for highly accurate detection of bladder cancer." (PMID 41228219, 2025). "Previous studies have reported that, P4HA2-mediated stabilization of HIF-1α promotes FGFR3 expression and increases erdafitinib resistance in bladder cancer." (PMID 40379610, 2025). "A known GWAS-identified bladder cancer susceptibility SNP, rs798766 of TACC3 (near FGFR3), was among SNPs associated with FAM53A expression in whole blood." (PMID 39789109, 2025). "The combination of the anti-FGFR3 enables the identification of bladder cancer cells while simultaneously inhibiting the proliferation of bladder cancer cell lines, ultimately leading to cellular apoptosis." (PMID 39896991, 2025). "explored the impact of FGFR3 alterations in bladder cancer TME and demonstrated that mutant FGFR3 indirectly induces an immunosuppressive TME by increasing serine synthesis." (PMID 41409251, 2025). "In terms of lipid metabolism, FGFR signaling has been shown to activate lipogenic pathways across multiple tumor models, particularly in FGFR3-altered bladder cancer." (PMID 41514604, 2025). "These robust results strongly suggest that the down-regulation of FGFR3 is a crucial molecular event for bladder cancer progression." (PMID 41228379, 2025). "Previous pre-clinical studies have linked higher expression of neighboring genes to FAM53A on 4p16.3, including TACC3 and FGFR3, to bladder cancer development and progression." (PMID 39789109, 2025). "In bladder cancer, FGFR3 can regulate PD-L1 ubiquitination and stability through phosphorylation of NEDD4, thereby affecting CD8+ T cell function." (PMID 41514604, 2025). "In FGFR3-mutant bladder cancers, concurrent PI3K/AKT activation predicts reduced response to FGFR inhibitors such as erdafitinib." (PMID 41438986, 2025). "A membrane-bound protein called fibroblast growth factor receptor 3 (FGFR3) is overexpressed in 20% of cases of advanced bladder cancer and aids in the development of aggressive tumors." (PMID 41283276, 2025). "Although FGFR3 alterations are common in early-stage bladder cancer, particularly in NMIBC, a distinct subset of MIBC displays FGFR1 amplification or overexpression." (PMID 41315241, 2025). "The mutation profiles of FGFR3 and TERT in ctDNA not only provide insights into tumor heterogeneity but also reflect the clonal evolution of bladder cancer." (PMID 40191434, 2025).